CD79A (CD79a molecule)
Diseases named in the same sentence as CD79A in open-access papers (continued):
Sharing a sentence is not in itself a finding about the gene and the disease.
acute myeloid leukemia (8 papers, 2008 to 2025). Acute myeloid leukemia (AML) is a group of neoplasms arising from precursor cells committed to the myeloid cell-line differentiation. "CD79a expression on myeloid cells was first reported in some cases of acute myeloid leukemia (AML) which showed co-expression of CD79a with myeloid markers." (PMID 24146823, 2013). "In Acute Myeloid leukemia with granulocytic maturation (AML-M2) patients, CD19 was reported in five cases and CD79a in one case." (PMID 40103873, 2025).
cervical carcinoma (7 papers, 1997 to 2025). A carcinoma arising from either the exocervical squamous epithelium or the endocervical glandular epithelium. "In the cervical cancer relevant immune microenvironment analysis, both CCR7 and CD79A were selected as representative genes concerning survival outcomes." (PMID 37988195, 2023).
lung adenocarcinoma (7 papers, 2019 to 2025). A carcinoma that arises from the lung and is characterized by the presence of malignant glandular epithelial cells. "As a proof of concept, we illustrate the cell sociology of CD3+ T cells, CD3+ CD8+ T cells, CD79a+ B cells, and unstained cells in full tissue sections of lung adenocarcinoma, revealing novel parameters that are important for anti-cancer immunity." (PMID 30651131, 2019). "We have developed a novel pipeline for hyperspectral imaging and cell sociology analysis of multiplexed IHC specimens, and applied it to 100 areas from 20 FFPE tumor sections of lung adenocarcinoma (CD3, CD8, CD79a, haematoxylin)." (PMID 30651131, 2019). "Tissue sections of primary tumors from lung adenocarcinoma patients with known clinical outcome were stained using multiplex IHC for CD3, CD8, and CD79a, and hyperspectral image analysis determined the phenotype of all cells." (PMID 30651131, 2019).
follicular lymphoma (6 papers, 2014 to 2025). Follicular lymphoma is a form of non-Hodgkin lymphoma characterized by a proliferation of B cells whose nodular structure of follicular architecture is preserved. "In the 5 patients with CD20 negative follicular lymphoma at tumor resample, the expression of other B-cells markers of FL by immunochemistry (CD79a and CD19) was assessed." (PMID 35582306, 2021). "Expression of B-cells markers in tumor cell surfaces (CD20, CD79a, CD10, CD19) in the CD20 negative patients with relapsed or refractory follicular lymphoma at resample time on fresh tumor biopsy." (PMID 35582306, 2021).
mantle cell lymphoma (6 papers, 2009 to 2025). Mantle cell lymphoma is a rare form of malignant non-Hodgkin lymphoma affecting B lymphocytes in the lymph nodes in a region called the ``mantle zone''. "Mantle cell lymphoma expresses B cell markers (CD20 and CD79a), T cell markers (CD5), and cyclin D1." (PMID 38698463, 2024). "Mantle cell lymphoma expresses B-lymphocyte markers (CD20 and CD79a), T-lymphocyte markers (CD5), and cyclin D1." (PMID 28705174, 2017). "The histo morphology and the immunophenotypic analysis were consistent with a mantle cell lymphoma – positive for Cyclin D1, CD20, CD79a and CD5; negative for BCL16, CD23 and CD10." (PMID 19646237, 2009).
oral squamous cell carcinoma (6 papers, 2017 to 2025). "Through gene expression analysis and clinical data, researchers have found that high expression of CD79A is associated with better prognosis in oral squamous cell carcinoma patients." (PMID 37884883, 2023). "CD79A was used as a B lymphocyte infiltration prognostic marker in oral squamous cell carcinoma." (PMID 40725191, 2025). "Studies have found that CD79A plays an important role in oral squamous cell carcinoma (OSCC) and may serve as a potential biomarker for treatment and prognosis." (PMID 37884883, 2023). "Immunohistochemistry of the pathological tissues after resection revealed that CD79A could be expressed to different degrees in oral squamous cell carcinoma tissues." (PMID 37344840, 2023). "Other works have identified B cells (CD79a and CD20 positive) in feline oral squamous cell carcinoma." (PMID 33919282, 2021).
Pleural effusion (6 papers, 2019 to 2025). The presence of an excessive amount of fluid in the pleural cavity. "Other factors associated with improved survival included the absence of CD138 expression (P = 0.0009), age ≥ 65 years (P = 0.0015), LDH ≤ 500 U/L (P = 0.0064), the presence of pleural effusion (P = 0.0099), and CD79a expression (P = 0.0411)." (PMID 41383509, 2025).
adenoma (5 papers, 2020 to 2025). A neoplasm arising from the epithelium. "Histochemical and immunohistochemical analyses of canine hepatoid gland tumours revealed that B cells, particularly those expressing CD79a, were significantly higher in adenomas and in the surrounding stroma of well-differentiated carcinomas, suggesting their protective role." (PMID 41040928, 2025).
aneurysm (5 papers, 2010 to 2022). Bulging or ballooning in an area of an artery secondary to arterial wall weakening. "The immunohistochemical staining was used to analyze the infiltration of pro-inflammatory (CD68) and anti-inflammatory macrophages (CD163), T helper (CD4) and T killer cells (CD8), and B (CD79a) and plasma cells (CD138) in all three layers of aneurysms of both groups." (PMID 34656077, 2022).
B-cell neoplasm (5 papers, 2009 to 2023). A group of heterogeneous lymphoid tumors generally expressing one or more B-cell antigens or representing malignant transformations of B-lymphocytes. "The B cell neoplasms were morphologically very heterogeneous but all were positive for CD79a (Igα) and/or B220." (PMID 20046882, 2009). "Immunophenotypically, cMCL is a mature B-cell neoplasm characterized by CD79a and CD20 expression." (PMID 28435836, 2016). "Like other mature B cell neoplasms, FL expresses pan-B cell antigens (CD19, CD22, CD79a and PAX5), and is also by definition positive for germinal center markers, such as BCL6, HGAL and LMO2." (PMID 34898578, 2021). "Phenotypically, hMCL is a mature B-cell neoplasm characterized by positivity for the B-cell markers CD19, CD20, CD22, CD79a, CD79b, with surface Ig expression and lambda light-chain restriction in approximately 2/3rds of cases." (PMID 28435836, 2016).
non-Hodgkin lymphoma (5 papers, 2017 to 2025). Distinct from Hodgkin lymphoma both morphologically and biologically, non-Hodgkin lymphoma (NHL) is characterized by the absence of Reed-Sternberg cells, can occur at any age, and usually presents as a localized or generalized lymphadenopathy associated with fever and weight loss. "In 2 of the 5 samples categorized as SFM, atypical lymphoid cells were observed, and as these cells were CD20- and CD79a-positive in the immunohistochemical examination performed with cell blocks, the samples were reported as suspicious for non-Hodgkin lymphoma." (PMID 40342313, 2025). "The diagnosis of this aggressive non-Hodgkin lymphoma typically involves the biopsy of suspicious lymph nodes or extranodal tumors, where the normal tissue architecture is replaced by sheets of large cells exhibiting positive staining for pan-B-cell antigens, like CD20 and CD79a." (PMID 39000261, 2024). "It resembles non-Hodgkin lymphoma (NHL), by expressing classic B cell markers such as CD20 and CD79a however lacks definitive HL markers (such as CD15 and CD30)." (PMID 29552367, 2018).
thymoma (5 papers, 2016 to 2025). A neoplasm arising from the epithelial cells of the thymus. "Conversely, high expression of CD79A was associated with higher odds of survival in thymomas (n = 118, HR = 0.11, 95% CI 0.03‐0.46, P < .001)." (PMID 32383556, 2020).
acute leukemia (4 papers, 2021 to 2025). A clonal (malignant) hematopoietic disorder with an acute onset, affecting the bone marrow and the peripheral blood. "CD79a is considered a B-cell antigen, but is often expressed in immature blast crisis acute leukemias following CML (chronic myeloid leukemia)." (PMID 36354555, 2022). "The European Group for the Immunological Characterization of Acute Leukemias (EGIL) selected CD79a as one of the most potent markers for B-lineage assessment in its proposed immunological classification table of acute leukemias." (PMID 34706776, 2021). "There were some aberrant markers which were present in more than one type of acute leukemia such that CD2 was present in B-ALL as well as in AML, CD79a was present in T-ALL as well as in AML and CD13 was present in both B-ALL and T-ALL." (PMID 40103873, 2025). "The WHO 2016 updated classification of hematological malignancies of myeloid neoplasms and acute leukemia has defined the criteria for assignment of the B-ALL lineage by FC on the basis of the intensity of expression of four key markers: CD19, CD79a, cytoplasmic CD22, and CD10." (PMID 34706776, 2021).
emphysema (4 papers, 2012 to 2023). "The expression of CD79A, a component of the B-cell receptor, increased in expression with increasing emphysema severity, and the expression of ACVRL1 (also known as activin-like kinase I), a receptor in the TGFβ pathway, decreased in expression with increasing emphysema severity." (PMID 22937864, 2012).
metastatic tumors (3 papers, 2012 to 2014). "Since we found that MDSCs expanded by metastatic tumors maintain the CD79a expression seen in immature BM cells, we asked whether CD79a plays a role in myeloid differentiation." (PMID 24146823, 2013). "The data thus far support the hypothesis that in mouse models of metastatic disease, the tumor can increase expression of CD79a on immature myeloid cells, thereby maintaining a more immature phenotype with immunosuppressive and tumor promoting characteristics." (PMID 24146823, 2013).
osteosarcoma (3 papers, 2021 to 2024). A usually aggressive malignant bone-forming mesenchymal neoplasm, predominantly affecting adolescents and young adults. "We developed a four-immune gene prognostic index of osteosarcoma, including CD79A, CSF3R, MTNR1B and NPPC." (PMID 33371790, 2021).
sarcoma (3 papers, 2015 to 2023). A usually aggressive malignant neoplasm of the soft tissue or bone. "CD45, CD20, CD79a, and PAX5 should be positive in DLBCL as in our case, while other markers for sarcoma including smooth muscle actin, muscle specific actin, and desmin should be negative." (PMID 25984371, 2015).
acute T-cell leukemia (2 papers, 2008 to 2012). "Immunophenotyping analysis of the bone marrow biopsy confirmed T-cell acute lymphoblastic leukemia, as CD3 and terminal deoxynucleotidyl transferase markers were positive and CD10, CD20 and CD79a markers were negative." (PMID 23057758, 2012).
breast tumor (2 papers, 2007 to 2013). "Furthermore, immunofluorescence staining of human breast tumor sections showed tumor infiltration by myeloid cells (CD11b+) that express CD79a." (PMID 24146823, 2013).
CNS lymphoma (2 papers, 2015 to 2019). "Interestingly, myeloid sarcomas can express B-cell antigens (e.g., CD19, CD79a) and, thus, potentially lead to a histologic misdiagnosis of CNS lymphoma, if no immunohistochemistry or flow cytometry analysis is available." (PMID 26239467, 2015).
lymphoid neoplasm (2 papers, 2021 to 2023). A neoplasm composed of a lymphocytic cell population which is usually malignant (clonal) by molecular genetic and/or immunophenotypic analysis. "We have reviewed the complex role of CD79a/CD79b in multiple aspects of normal B cell biology and how is the normal BCR signaling affected by lymphoid neoplasms associated CD79A/CD79B mutations." (PMID 38203179, 2023). "As a result, many cases of aberrant expression of CD79a in other myeloid and lymphoid tumors have been reported." (PMID 34706776, 2021).
lymphoplasmacytic lymphoma (2 papers, 2013 to 2024). A clonal neoplasm of small B-lymphocytes, lymphoplasmacytoid cells, and plasma cells involving the bone marrow, lymph nodes, and the spleen. "The immunohistochemistry revealed positive staining for CD20, CD79a, and Lambda of B cell markers and negative for CD38 and CD138 of plasma cells, and so this patient was diagnosed with lymphoplasmacytic lymphoma." (PMID 24385833, 2013).
non-small cell lung carcinoma (2 papers, 2021 to 2025). A group of at least three distinct histological types of lung cancer, including non-small cell squamous cell carcinoma, adenocarcinoma, and large cell carcinoma. "According to recent publications, CD79A has a specific expression level in carcinoma-associated fibroblasts in non-small cell lung cancers." (PMID 34575089, 2021).
renal carcinoma (2 papers, 2021 to 2025). A carcinoma arising from the epithelium of the renal parenchyma or the renal pelvis. "Together, these findings confirmed the relationship of PTP4A3 to immune cell infiltration and CD79A, CSF1R, INOS, COX2, STAT5A, FOXP3 and CCR8 in KIRP, suggesting an important immune regulation role of PTP4A3 in the renal cancer microenvironment." (PMID 34630392, 2021).
synovitis (2 papers, 2012 to 2023). Inflammation of a synovial membrane. "In addition, the density of subintimal common mononuclear inflammatory cell types, including CD68+ cells, CD3+ cells, CD38+ cells, CD20+ cells, and CD79a+ cells, were significantly higher in high-grade synovitis RA patients than that in low-grade synovitis RA patients." (PMID 22656185, 2012).
Achalasia (1 paper, 2016). A disorder of esophageal motility characterized by the inability of the lower esophageal sphincter to relax during swallowing and by inadequate or lacking peristalsis in the lower half of the body of the esophagus. "Interestingly, in our results, IRF4 and BLIMP1 are important upstream regulators of genes down-regulated, such as XBP1, IGHM, CD79A, RORC, and IKZF2, stressing the implications of the immune-inflammation network in achalasia." (PMID 27511445, 2016).
B-cell precursor acute lymphoblastic leukemia (1 paper, 2023). "As a signal transduction component of the pre-B-cell receptor, CD79A promotes the infiltration and recurrence of B-cell precursor acute lymphoblastic leukemia in the central nervous system." (PMID 37344840, 2023).
hepatoid carcinomas (1 paper, 2025). "Immunohistochemical analysis of ten hepatoid adenomas, thirteen well-differentiated hepatoid carcinomas and nine undifferentiated hepatoid carcinomas revealed that adenomatous structures exhibit the greatest concentration of CD79a-positive, IgA-producing B cells." (PMID 41040928, 2025).
jaw cysts (1 paper, 2026). "The identified 6 proteins, namely CD79A, CD5, KRR1, UTP20, AATF, and WDR43 - may be closely associated with the pathogenesis of jaw cysts." (PMID 42175431, 2026).
laryngeal tumor (1 paper, 2024). "Postoperative IHC results of the laryngeal tumor were as follows: CD20 (+), CD79a (+), CD3 (−), CD10 (−), Bcl-2 (+), CD5 (−), Cyclin D1 (−), and CD23 (−)." (PMID 39290501, 2024).
Lewis Lung carcinoma (1 paper, 2013). "In the transplantable metastatic Lewis Lung carcinoma (LLC) model which is syngeneic to C57Bl/6, peripheral myeloid cells expanded by the tumor expressed CD79a (detected by CD79-11)." (PMID 24146823, 2013).
marginal zone B-cell lymphoma (1 paper, 2013). "Severe infiltration of medium-sized lymphocytes with strong positive immunoreactivity for CD79a and numerous anaplastic features was detected in the unilateral uterine horn, and the dog was diagnosed as having extranodal marginal zone B-cell lymphoma (MZBCL)." (PMID 24325894, 2013).
meningioma (1 paper, 2025). A generally slow growing tumor attached to the dura mater. "This was considered an unlikely diagnosis in this case as the CD79a immunoreactive round cells had a very high mitotic count and showed features of cellular atypia that would not be expected in a lymphoplasmacyte-rich meningioma." (PMID 40852427, 2025).
Moyamoya disease (1 paper, 2013). Moyamoya disease (MMD) is a rare intracranial arteriopathy involving progressive stenosis of the cerebral vasculature located at the base of the brain causing transient ischemic attacks or strokes. "We identified 165 significantly (p < 0.05) elevated autoantibodies in Moyamoya Disease, including those against CAMK2A, CD79A and EFNA3." (PMID 23518061, 2013).
splenic marginal zone lymphoma (1 paper, 2022). Splenic marginal zone lymphoma is a rare, indolent B-cell non-Hodgkin lymphoma characterized by abnormal clonal proliferation of mature B-lymphocytes with involvement in the spleen, bone marrow and, frequently, the blood. "Bone marrow biopsy revealed proliferation of atypical lymphocytes, and immunostaining was positive for Cluster Designation (CD)79a, CD20, and bcl‐2, which led to a diagnosis of splenic marginal zone lymphoma (SMZL)." (PMID 35310319, 2022). "Bone marrow biopsy showed CD79a, CD20, and bcl‐2‐positive atypical lymphocytes, which led to the diagnosis of splenic marginal zone lymphoma." (PMID 35310319, 2022).
T cell neoplasms (1 paper, 2021). "CD79a is part of the B cell receptor, and most T cell neoplasms do not express CD79a proteins." (PMID 33371790, 2021).
infection (2,244 papers, 1997 to 2026). The state of being infected such as from the introduction of a foreign agent such as serum, vaccine, antigenic substance or organism. "Significantly downregulated of key components of TCR and BCR signaling pathways, such as ZAP70, BTK, and CD79A, suggested a temporary inhibition of these pathways critical for cellular immunity post-infection." (PMID 39650642, 2024). "This analysis confirmed that during infection there was an upregulation of both Cd79a+Il10+ Bregs (p < 0.02, Mann–Whitney test) and Cx3cr1+Il10ra+ microglia (p < 0.01, Mann–Whitney test)." (PMID 38594373, 2024). "B cell (CD79a+) numbers also showed a marked drop 2 days after infection, to 50–70% of mock-infected levels." (PMID 24968319, 2014). "CD79A was significantly downregulated in severe cases, correlating with impaired B-cell responses and cytotoxic immunity, while GADD45A, upregulated in severe infections, linked to oxidative stress and neutrophil-driven inflammation." (PMID 40677720, 2025). "Correlations were also found between Cd19 (R = 0.9134), Cd79a (R = 0.9865), Cd79b (R = 0.9620) and the apoptotic protein Bik, which may be involved in the B cell depletion during infection." (PMID 36400767, 2022). "This kind of cells was evaluated using CD-79a antibodies: even if not well understood, this kind of investigation could be used in order to likely distinguish between the two patterns of the same infection." (PMID 32784826, 2020). "The location of S. stercoralis, within colonic nodules consisting of epithelial hyperplasia and cells staining positive for CD3 (T-cells), and the CD79a staining of the intranodular Strongyloides stages observed, may provide new insight to the pathogenesis of this infection." (PMID 31300009, 2019). "Previous studies have identified immune-related genes, such as IFNs and chemokines, as potential biomarkers for RSV severity.However, the novelty of CD79A and GADD45A lies in their specific association with hospitalization needs rather than general infection status." (PMID 40677720, 2025). "Together, interactions among multiple molecules consisting of this network, such as CD19, CD 22, and CD79A/B, and chemokines including CCL19, CCL22, and CXCL13 may contribute to enhanced immune responses in the resistant line in the HSF flock to the innate infection." (PMID 30678719, 2019). "Furthermore, the investigation of downstream genes implicated in BCR signal transduction, including syk, btk, akt, blyk, lyn, p38, CD79a/b, ZAP-70, RAS, etc., exhibited no changes in expression in response to the SAV3 infection." (PMID 39691715, 2024).